MDM2 (MDM2 proto-oncogene)
Diseases named in the same sentence as MDM2 in open-access papers (continued):
Sharing a sentence is not in itself a finding about the gene and the disease.
hematological malignancies (23 papers, 2012 to 2026). "Mouse double minute 2 homolog (MDM2) is an E3 ubiquitin ligase that is associated with radio/chemotherapy resistance in several hematological malignancies." (PMID 35326742, 2022). "The aim of this study was to identify subsets of patients with hematological malignancies susceptible to the combined treatment with the MCL1 antagonist S63845 in combination with the MDM2-inhibitor HDM201 or the MEK-inhibitor trametinib." (PMID 31718075, 2019). "Ongoing trials will further clarify the role of MDM2 inhibition across solid and hematologic malignancies." (PMID 41515979, 2025). "Low objective response rates for patients with solid tumors have also been reported for other MDM2 inhibitors, while response rates for hematological malignancies like AML have been modestly higher for some agents studied." (PMID 39510293, 2024). "In this regard, a novel MDM-2 inhibitor (RG7112) with superior bioavailability with respect to Nutlin-3 is currently under evaluation in clinical trials in patients with hematologic malignancies." (PMID 27661115, 2016). "Therefore, MDM2 inhibitors have been tested in preclinical studies and some of them are under clinical investigation for solid tumors and hematological malignancies." (PMID 38396916, 2024). "Collectively, these different studies indicated that MDM2 inhibition could be a new promising target therapy in hematological malignancies." (PMID 28018226, 2016). "AMG-232 has also shown activity against both MDM2 and MDM4 in preclinical studies and is currently being evaluated in clinical trials for hematologic malignancies." (PMID 39538363, 2024). "Additionally, combination therapies with other agents may enhance the efficacy of MDM2 and MDM4 inhibitors and improve outcomes for patients with hematologic malignancies." (PMID 39538363, 2024).
adenocarcinoma (15 papers, 1997 to 2025). A common cancer characterized by the presence of malignant glandular cells. "71.4%of APT121;Mdm2+/+ mice developed adenocarcinomas compared with only 37.5%of APT121;Mdm2C305F/C305F mice." (PMID 21747916, 2011). "Notably, one adenocarcinoma cluster was defined by an extensive MDM2 signaling, restricted to this cluster alone." (PMID 40833530, 2025). "Secondly, all the four documented MDM2-amplified PSCs had adenocarcinoma components." (PMID 36059611, 2022). "Several of the identified mGISTIC regions harbored known or putative adenocarcinoma driver candidates, such as EGFR, MDM2, KRAS, MYC, TERT, MET, CCND1, NKX2-1/TITF1, CDK4, ERBB2, ID1, RB1, CDKN2A and PTEN." (PMID 24205279, 2013).
metabolic disease (10 papers, 2012 to 2025). A congenital disorder (due to inherited enzyme abnormality) or acquired (due to failure of a metabolically important organ) disorder resulting from an abnormal metabolic process. "Evaluating whether some of these polymorphisms also correlate with metabolic phenotypes may unravel new interesting connections between MDM2/MDM4 and metabolic diseases." (PMID 33406607, 2021). "Therefore, hepatic MDM2 and its ability to suppress ApoB expression are potential pharmacological targets for the treatment of MAFLD, a metabolic disease currently lacking any effective treatment." (PMID 35524581, 2022).
neurodegenerative disease (10 papers, 2010 to 2025). A disorder of the central nervous system characterized by gradual and progressive loss of neural tissue and neurologic function. "As p38 MAPK and Mdm2 have also been shown to participate in pathogenesis associated with other neurodegenerative diseases, our results could have significant implications for a better understanding of a wide range of neurodegenerative diseases." (PMID 20386595, 2010). "According to published studies, MDM2 inhibition is a potential therapeutic candidate for degenerative diseases through promoting the apoptosis of senescent cells." (PMID 39755936, 2025). "In addition, EGCG was found to modulate expression of proapoptotic genes like Bax, Bad, and Mdm2 whilst genistein induced changes in the expression of the Bcl-2 gene, thereby increasing survival of cells in neurodegenerative diseases." (PMID 26576219, 2015).
hematological cancers (9 papers, 2010 to 2025). "However, the mechanisms by which hematopoietic neoplasms upregulate MDM2 are largely unknown, and the mechanism by which AML1-ETO induces MDM2 expression also remains to be determined." (PMID 20805992, 2010).
kidney (8 papers, 2009 to 2025). "To verify that the changes in the brain inflammatory signaling milieu that we observed in the Mdm2-cKO mice could be due to common types of severe kidney tubular injury, we analyzed plasma samples of a mouse model of severe ischemic kidney injury." (PMID 39946208, 2025). "In order to induce acute kidney injury and to investigate MDM2 inhibitory effects, we injected cisplatin into rats with or without the MDM2 inhibitor, DS‐5272, and analyzed kidney physiology/histology and NFκB signaling." (PMID 30564368, 2019).
neurological diseases (6 papers, 2016 to 2025). "In addition, CHIP belongs to the same protein family as MDM2 (E3 ubiquitin ligases) and has potential therapeutic relevance by being implicated in neurological disease." (PMID 38418820, 2024).
cardiovascular diseases (5 papers, 2019 to 2024). "Additional investigations are required to fully comprehend how GSK3 and Akt impact MDM2 function in the context of these cardiovascular diseases." (PMID 31921839, 2019).
kidney disease (4 papers, 2017 to 2025). "Meanwhile, MDM2 dysregulation is also implicated in the pathological events of various kidney diseases." (PMID 28871126, 2017). "The role of MDM2 in kidney diseases has been studied extensively, and we described the pathogenic effect of MDM2 in DKD here, showing that inhibition of MDM2 alleviated pathological injury in podocytes under diabetic conditions." (PMID 40421968, 2025). "However, published studies show that the pathologic role of MDM2 in kidney disease is controversial and that its inhibition may not always be beneficial." (PMID 40421968, 2025).
blood cancer (3 papers, 2018 to 2022). "MDM2 also possesses multiple function in hematological neoplasms." (PMID 35628480, 2022). "In addition, Nutlin-3 can also induce the formation of heat shock protein 70 (HSP70)-MDM2 foci, consistent with a recent report that demonstrated induction of MDM2 and HSP70 in blood cancer cells in response to the Nutlin ligand." (PMID 32874188, 2020).
gastrointestinal tumors (3 papers, 2023 to 2025). "Studies suggested that non-canonical PTMs such as SENP2 mediated de-SUMOylation of N-myc, Mdm2 regulated neddylation of HuR, and PADI4 promoted histone citrullination of NETs contribute to the progression of gastrointestinal tumors." (PMID 37777749, 2023).
heart disease (2 papers, 2025). "MDM2’s Influence on GRK2 Activity: MDM2 has been shown to regulate cardiac contractility by inhibiting GRK2-mediated desensitization of β-adrenergic receptors, highlighting its potential as a therapeutic target in heart diseases." (PMID 40244017, 2025).
inflammation (2 papers, 2024 to 2025). Aberrant reaction of the microcirculation characterized by movement of fluid and leukocytes from the blood into extravascular tissues. "As kidney inflammation can contribute to systemic inflammation through the release of inflammatory mediators, we found an elevated neutrophil-to-lymphocyte ratio in the Mdm2-cKO mice compared with the control group (P = 0.02) and a significant increase in plasma IL-6 protein levels." (PMID 39946208, 2025).
MDM2 also shares sentences with these, for which no sentence is quoted: myxofibrosarcoma (7 papers); well-differentiated liposarcoma (7); papillary thyroid carcinoma (6); parosteal osteosarcoma (6); benign tumors (5); pleomorphic liposarcoma (4); urothelial carcinoma (4); uterine fibroids (4); chondroblastoma (3); chronic kidney disease (3); endometrial stromal sarcoma (3); type 1 diabetes (3); Ad- (2); Angelman syndrome (2); bone sarcoma (2); cardiomyopathy (2); chronic hepatitis B (2); colorectal adenocarcinoma (2); diffuse intrinsic pontine glioma (2); endometrial stromal tumor (2); fibroma (2); follicular lymphoma (2); IgG4-related disease (2); Intellectual disability (2); leukopenia (2); malignant mesothelioma (2); mesenchymal chondrosarcoma (2); metabolic syndrome (2); metastatic cancer (2); Osteoblastoma (2).
A further 153 diseases each share a sentence with MDM2 in 2 papers or fewer.